OLFM4 (olfactomedin 4)
Diseases named in the same sentence as OLFM4 in open-access papers (continued):
Sharing a sentence is not in itself a finding about the gene and the disease.
clear cell renal carcinoma (1 paper, 2022). A malignant epithelial neoplasm of the kidney characterized by the presence of lipid-containing clear cells within a vascular network. "We identified five survival-related genes (AGR2, HAO2, IGF2BP1, MCCD1 and OLFM4) in clear cell renal carcinoma patients." (PMID 36516496, 2022).
Crohn disease (1 paper, 2024). A gastrointestinal disorder characterized by chronic inflammation involving all layers of the intestinal wall, noncaseating granulomas affecting the intestinal wall and regional lymph nodes, and transmural fibrosis. "Importantly, OLFM4+ epithelial cells, which are involved in digestive diseases and active lesions of Crohn's disease, were mainly present in the GSD‐Ib group compared with the other groups." (PMID 38889269, 2024).
dengue (1 paper, 2015). "Analysis of a selection of the identified proteins using ELISAs identified two host proteins, OLFM4 and PF4, which had significant prognostic value for classifying patients with dengue who were likely to develop SD." (PMID 26572220, 2015). "Further prospective studies are warranted to confirm and validate the prognostic value of OLFM4 and PF4 as potential biomarkers of disease severity in larger cohorts of patients from a variety of dengue-endemic areas around the globe." (PMID 26572220, 2015).
endometriosis (1 paper, 2014). The growth of functional endometrial tissue in anatomic sites outside the uterine body. "This study also showed OLFM4 transcription to be up-regulated in the endometrium of patients with endometriosis." (PMID 24495253, 2014).
gastric MALT lymphoma (1 paper, 2023). "Olfactomedin-4 and Nanog homeobox were positive and negative predictive factors, respectively, for eradication therapy efficacy against gastric MALT lymphoma; they were negative for both API2-MALT1 and Hp." (PMID 36831547, 2023). "OLFM4 and NANOG could be positive and negative predictive markers, respectively, for eradication therapy efficacy against gastric MALT lymphoma that is negative for both API2-MALT1 and Hp infection." (PMID 36831547, 2023).
generalized pustular psoriasis (1 paper, 2022). A rare and extreme form of psoriasis characterized by the appearance of sterile pustules which can take many patterns. "A recent report has suggested that OLFM4 may have a role in the pathogenesis of generalized pustular psoriasis by activating keratinocytes via neutrophil-derived exosomes." (PMID 35218417, 2022).
glaucoma (1 paper, 2014). Increased pressure in the eyeball due to obstruction of the outflow of aqueous humor. "Several members of the family have been implicated in various common diseases, notably myocilin in glaucoma and OLFM4 in cancer." (PMID 25364714, 2014).
glioblastoma (1 paper, 2015). The most malignant astrocytic tumor (WHO grade IV). "Currently, the expression pattern and the biological roles of OLFM4 in glioblastoma cells remain unknown." (PMID 25797252, 2015). "OLFM4 proteins might play anti-apoptotic roles in RA-treated glioblastoma cells but are not sufficient to rescue decitabine-pretreated LN428 and U251 cells from RA-induced apoptosis." (PMID 25797252, 2015).
head and neck cancer (1 paper, 2023). A primary or metastatic malignant neoplasm affecting the head and neck. "OLFM4 is produced by neutrophils and has been described as a biomarker of inflammation in auto-immune diseases and in cancer, notably in whole saliva from head and neck cancer compared to pSS patients." (PMID 37529039, 2023).
invasive carcinoma (1 paper, 2025). A carcinoma that is not confined to the epithelium, and has spread to the surrounding stroma. "Differential gene expression analysis comparing MCNs with their associated invasive carcinomas identified two significantly overexpressed genes in MCNs: OLFM4 and MUC5B." (PMID 40371932, 2025).
Lassa fever (1 paper, 2021). A viral hemorrhagic fever that is caused by the Lassa virus, which is transmitted by contact with infected rodents; it is characterized by fever, headache, malaise, myalgia, and hearing loss. "Genes involved in extracellular matrix and cell-adhesion were also modulated, particularly during fatal Lassa fever (NID1, TIMP3, ITGA11, TGM2, MMP8/9, OLFM4, PCDH20, and CADM3), as well as some others involved in coagulation (SERPIN, TFPI2) and apoptosis (CLU, BCL2L14)." (PMID 33398113, 2021).
malaria (1 paper, 2022). Malaria is a serious and sometimes fatal disease caused by a parasite that commonly infects a certain type of mosquito which feeds on humans. "It has been reported that the neutrophil granule proteins MMP8, OLFM4, DEFA3, and ELANE are increased in severe malaria versus uncomplicated malaria." (PMID 36380373, 2022).
MALT lymphoma (1 paper, 2023). An indolent, extranodal type of non-Hodgkin lymphoma composed of small B-lymphocytes (centrocyte-like cells). "In this study, OLFM4 was extracted as a positive predictive marker for the efficacy of eradication therapy in Hp-negative gastric MALT lymphoma." (PMID 36831547, 2023).
measles (1 paper, 2015). A highly contagious viral infection caused by the measles virus. "In contrast, two other studies did not observe upregulation of OLFM4 in PBMCs from children during infection by measles or rotavirus (GSE 5808 and 2729)." (PMID 26162090, 2015).
morbid obesity (1 paper, 2022). An excess of body weight, normally defined as an individual with a body mass index greater than 35 or a body weight greater than one hundred percent of ideal body weight. "Thus, the current study aimed to analyse OLFM2 mRNA expression in liver biopsies and OLFM4 mRNA expression in jejunum samples in a well-established cohort of women with morbid obesity (MO) with different NAFLD grades to explore the role of OLFMs in the pathogenesis of NAFLD." (PMID 35806447, 2022).
multiple myeloma (1 paper, 2025). "Likewise, exosomes from platelets in patients with multiple myeloma presented elevated levels of leucine-rich alpha-2-glycoprotein 1 (LRG1), which interacts with Olfactomedin 4 (OLFM4) in tumor cells, activating the EMT signaling pathway." (PMID 39934930, 2025).
non-small cell lung carcinoma (1 paper, 2021). A group of at least three distinct histological types of lung cancer, including non-small cell squamous cell carcinoma, adenocarcinoma, and large cell carcinoma. "In fact, OLFM4 serum level has been a biomarker for several diseases, including asthmatics, non-small-cell lung cancer, pancreatic cancer, head and neck cancer, and prostate cancer." (PMID 34912753, 2021). "The OLFM4/HIF-1α axis was found to be involved in the regulation of hypoxia-induced invasion, epithelial-mesenchymal transition, and chemotherapy resistance in non-small-cell lung cancer." (PMID 34912753, 2021). "Interestingly, it was found that inhibition of the OLFM4/HIF-1α axis could improve hypoxia-induced invasion, epithelial-mesenchymal transition, and chemotherapy resistance of non-small-cell lung cancer." (PMID 34912753, 2021).
plaque psoriasis (1 paper, 2022). "In this work we showed that OLFM4 protein was considerably upregulated in the lesional skin of plaque psoriasis patients." (PMID 35218417, 2022).
prostatic intraepithelial neoplasia (1 paper, 2015). "Prostatic epithelial hyperplasia was seen at 3–6 months of age, prostatic intraepithelial neoplasia was observed at 10–12 months of age, and higher-grade prostate intraepithelial neoplasia was observed at 18–24 months of age in Olfm4-knockout mice." (PMID 26581960, 2015). "The frequency of prostatic intraepithelial neoplasia lesions was increased in Olfm4+/− and Olfm4−/− mice compared with Olfm4+/+ mice at ages 13–24 months." (PMID 26581960, 2015). "Higher-grade prostatic intraepithelial neoplasia (HG-PIN), as well as inflammatory cells, was observed in the DLP of Olfm4-knockout mice at 20 months of age." (PMID 26581960, 2015).
Respiratory Syncytial Virus infection (1 paper, 2015). "Interestingly, a recent paper mentioned the interest of OLFM4 as a marker of disease severity in Respiratory Syncytial Virus infection in children." (PMID 26572220, 2015).
Respiratory tract infection (1 paper, 2015). An infection of the upper or lower respiratory tract. "As both SAM and PAM analyses revealed OLFM4 as a potentially important marker for disease severity in children with RSV infection and OLFM4 has-to the best of our knowledge- not been associated with respiratory tract infections before, this gene was chosen for further analysis." (PMID 26162090, 2015).
serous adenocarcinoma (1 paper, 2016). An adenocarcinoma that is characterized by the presence of papillary patterns and cellular budding. "There was also a difference in OLFM4 expression between well- and poorly-differentiated serous adenocarcinomas (P < 0.001)." (PMID 26871282, 2016). "Staining intensity of OLFM4 decreased along with the degree of differentiation of serous adenocarcinoma." (PMID 26871282, 2016). "OLFM4 expression in well-differentiated serous adenocarcinoma was higher than normal ovarian epithelium (P < 0.001), indicating an association of OLFM4 expression with ovarian tumorigenesis." (PMID 26871282, 2016). "To investigate whether olfactomedin 4 (OLFM4) is associated with ovary tumorigenesis, we examined its expression in normal ovary; serous cystadenoma; serous borderline tumor; and well-, moderately- and poorly-differentiated serous adenocarcinoma using immunohistochemistry (IHC)." (PMID 26871282, 2016).
sleep disorder (1 paper, 2025). A change from the patient's baseline sleeping pattern, in the hours slept and/or an alteration/dysfunction in the stages of sleep. "We observed 142 associations including at known loci for sleep disorders (e.g. MEIS1, CACNA1C, OLFM4, PAX8 and TCF4)." (PMID 41332830, 2025).
uterine cancer (1 paper, 2023). Primary or metastatic malignant neoplasm involving the uterine corpus and/or the cervix. "Based on our identification of OLFM4 as a cancer marker, we then tested for the presence of uterine cancer by immunoblotting." (PMID 37856394, 2023). "OLFM4 expression in LE and GE was variable across animals, with a direct correlation between extent of uterine cancer and extent of OLFM4 staining." (PMID 37856394, 2023). "To test whether PI3K/AKT signaling was activated in DES-induced uterine cancer cells, we localized OLFM4 and phosphorylated AKT (pAKT) in adjacent sections." (PMID 37856394, 2023). "Because DES-exposed CD-1 mice only develop localized foci of uterine adenocarcinoma by 12 months of age, we further explored the correlation of OLFM4 and pAKT in a more robust model of developmental DES-induced uterine cancer." (PMID 37856394, 2023).
uterine tumours (1 paper, 2014). "The expression of OLFM4 in uterine tumour was 2.4-fold that in uterus, indicating that OLFM4 transcription is up-regulated in uterine tumours." (PMID 24495253, 2014).
volvulus (1 paper, 2022). "Expression of OLFM4 and LYZ was higher in patients with NEC in comparison to control infants suffering from volvulus (median score of the antibody OLFM4 (D1E4M): 1.25 and lysozyme: 2.0)." (PMID 35410162, 2022).
tumor (82 papers, 2010 to 2025). "A an extracellular matrix glycoprotein containing distinctive N-linked carbohydrate chains and olfactomedin-like domains, OLFM4 has emerged as a critical regulator of oxidative stress responses and tumor progression." (PMID 40422535, 2025). "PI3K mutation upregulates OLFM4, which promotes tumor cell adhesion and proliferation and suppresses apoptosis in CRC." (PMID 41009348, 2025). "DEFA4 encodes a member of defensins thought to be associated with host defense and OLFM4 encodes an anti-apoptotic factor that promotes tumor growth." (PMID 33445803, 2021). "In tumors, increased OLFM4 expression is associated with differentiation, staging, metastasis, and poor prognosis, suggesting potential clinical value as a tumor marker in the early stages of carcinogenesis." (PMID 30944407, 2019). "We observed both increased lysozyme‐positive cell abundance and zone of OLFM4 expression in Huwe1‐deficient tumours." (PMID 28003334, 2017). "Previous clinical correlation analysis revealed that reduction of OLFM4 expression was associated with poor differentiation, late tumor stage and poor survival, which was consistent with our findings." (PMID 27294866, 2016). "The lowest 'C'/'E' expression ratio was observed for OLFM4 (50-fold decrease), encoding olfactomedin 4, an antiapoptotic factor that promotes tumor growth." (PMID 25476127, 2014). "This analysis uncovered 2 tumor-associated epithelial populations, including a tumor-specific stem-like (tSTM, cluster 0) state defined by OLFM4 and LGR5, and a tumor-specific deep crypt secretory (tDCS, cluster 10) state characterized by REG4 with limited MUC2." (PMID 41282138, 2025). "Furthermore, expression of the OLFM4 gene associated with nodal metastasis was focused within a single tumor-associated cluster and indicates the potential of single cell analysis to define clusters associated with specific clinical features." (PMID 36253784, 2022). "In addition, OLFM4 expression (P=0.001) as well as tumor size (P=0.035) and intravascular tumor thrombi (P=0.045) were also associated with the number of lymph nodes with metastasis." (PMID 27294866, 2016). "Moreover, in the T1a and T1b subgroups of EGC, LNM was only associated with OLFM4 expression (P=0.01) in T1a patients and closely related to intravascular tumor thrombi (P=0.042) and OLFM4 expression (P=0.027) in T1b patients." (PMID 27294866, 2016). "In this study, we examined the potential functions of the Olfm4 gene in murine prostate tissues by analyzing an Olfm4-knockout mouse model, and found that loss of Olfm4 leads to neoplastic progression in the mouse prostate, as well as tumor formation in the lung, liver, and pancreas." (PMID 26581960, 2015). "OLFM4 encodes an anti-apoptotic protein that promotes tumor growth." (PMID 26540294, 2015). "Moreover, OLFM4, which is linked to tumor stemness and poor prognosis, was significantly expressed." (PMID 39840062, 2024). "Third, the possible cross-talk between OLFM4-mediated resistance pathways and tumor microenvironment (TME) factors merits further investigation." (PMID 40422535, 2025). "Studies have shown that DC vaccines loaded with OLFM4 can induce a potent immune response specifically against CSCs, thereby reducing tumor recurrence and metastasis." (PMID 39861713, 2025). "The current findings demonstrate that OLFM4 not only drives aggressive tumor behavior but also mediates cisplatin resistance through novel molecular mechanisms, positioning it as a promising therapeutic target for HNSCC." (PMID 40422535, 2025). "OLFM4 is overexpressed in many tumor tissues compared to normal counterparts, making it an attractive target for immunotherapy." (PMID 39861713, 2025). "CSCs express specific markers, such as OLFM4, that distinguish them from the bulk of tumor and normal cells." (PMID 39861713, 2025).
tumor (continued). "This study confirms that OLFM4 enhances tumor cell proliferation, migration, and resistance to cisplatin-induced cell death, thereby promoting HNSCC progression." (PMID 40422535, 2025). "This study examines the potential of combining mechanical high-intensity focused ultrasound (M-HIFU) with dendritic cell (DC) vaccines to enhance immune responses against OLFM4-expressing tumors, a CSC marker linked to immune evasion and tumor growth." (PMID 39861713, 2025). "This process is particularly beneficial for targeting OLFM4+ CSCs, as it reveals tumor antigens critical for enhancing the efficacy of DC vaccines." (PMID 39861713, 2025). "Tumor-specific stem-like cells (tSTM, cluster 0) exhibited strong upregulation of OLFM4, LEFTY1, SOD3, LCN2, SLC12A2, and MMP7, consistent with proliferative, inflammatory, and invasive phenotypes." (PMID 41282138, 2025). "OLFM4-specific cytotoxicity of cells from the inguinal lymph nodes was evaluated using an S.C. tumor model." (PMID 39861713, 2025). "This study sheds light on the significance of cell-cell interaction between OLFM4+ cancer stem cells and Paneth-like cells on tumor homeostasis." (PMID 38182890, 2024). "Our results are in agreement with previous findings that demonstrated a role for OLFM4 in promoting tumour cell adhesion and migration." (PMID 35218417, 2022). "OLFM4 consists of an antiapoptotic factor that promotes tumor growth and also an extracellular matrix glycoprotein that facilitates cell adhesion." (PMID 34997134, 2022). "The first consisted of CEACAM5 and CEACAM6 expressing tumour cells, colonic stem cells with high expression of OLFM4 and HIST1H4C." (PMID 35860583, 2022). "Our results showed that AML and CML differ in the expression of GBF1, CD177, OLFM4 and peptidylprolyl isomerase B (PPIB) implicated in the intercellular interactions and chemotaxis regulation to regulate tumor cell migration and invasion." (PMID 36230605, 2022). "With the exception of Olfm4, the expression of markers for active (Lgr5) and quiescent (Hopx) stem cell populations were maintained in tumor organoids, even at the highest CAP dose (80 W)." (PMID 35169122, 2022). "In agreement with this, we observe increased number of both pPDH+ cells and crypt base columnar (CBC) ISCs (positive for Olfm4) upon SIRT6 loss, which translates into enhanced tumor initiating potential." (PMID 35314684, 2022). "Collectively, OLFM4 has a diagnostic value to predict HCC, and it significantly correlated to tumor size." (PMID 34912753, 2021). "OLFM4 mRNA expression in HCC tissue was significantly correlated to tumor size (R2 = 0.5113, P < 0.0001)." (PMID 34912753, 2021). "We also detected two WNT mediators of GPX2 and OLFM4, which can be activated by Lgr5 to drive tumor progression." (PMID 34764257, 2021). "Because the primary and metastatic/recurrent PDOs were cultured in identical medium, our findings showing different expression of OLFM4 represent the intrinsic properties of tumor cells." (PMID 33711267, 2021). "OLFM4 staining was observed at the cell membrane and in the cytoplasm of tumor cells, and OLFM4 was also expressed in some stromal cells and normal glandular tissues." (PMID 31923206, 2020). "Chemoresistance was observed by in vitro analysis of tumor cell lines with forced expression of OLFM4." (PMID 31923206, 2020). "OLFM4 has been attributed oncogenic properties as it was shown to promote tumor growth by acting as an anti-apoptotic protein and by increasing the mitotic activity of cancer cells." (PMID 31283789, 2019).